BRCA1 (BRCA1 DNA repair associated)
Diseases named in the same sentence as BRCA1 in open-access papers (continued):
Sharing a sentence is not in itself a finding about the gene and the disease.
breast cancer (continued). "Variants in the breast cancer susceptibility genes BRCA1 and BRCA2 increase the risk of developing breast and ovarian cancers." (PMID 33081408, 2020). "These mice developed mammary tumors at a low frequency (approximate 25%) after long latency (two years), suggesting other factors are also involved in Brca1-mutation-dependent breast tumorigenesis." (PMID 32785175, 2020). "Outstanding examples can be found in the detection of the BRCA1 mutation as a marker of a high risk of ovarian or breast cancer or monitoring of the PSA antigen for the diagnostic of prostate cancer." (PMID 31936310, 2020). "The Most of the breast cancer-causing mutations in BRCA1 gene lead to produce truncated protein through the nonsense, frame shift and splicing mutations." (PMID 32856854, 2020). "In many other cancer types, the analysis of BRCA1/2 mutation has been used in clinical practice as a predictive marker for breast cancer and effectively improves the 5-year survival rate of patients." (PMID 33304845, 2020). "Control women were more likely than cases to have a family history of breast cancer, BRCA1 and BRCA2 mutations, a history of LCIS and a history of benign breast disease." (PMID 33287857, 2020). "The cumulative breast cancer risk at 40 years of age is approximately 24% for BRCA1 carriers and 13% for BRCA2 carriers." (PMID 32419845, 2020). "About 5% of all breast cancer cases are associated with pathogenic variants of DNA repair-associated breast cancer type 1 (BRCA1) susceptibility, and BRCA2 genes." (PMID 32456160, 2020). "In contrast, recent work showed an increase in luminal progenitor numbers in the breast tissue of BRCA1 mutation carriers and a correlation between the gene expression profile of normal human luminal progenitors and basal-like breast cancers." (PMID 32863939, 2020). "Roughly, 70% breast cancers evolving in BRCA1 mutation carriers while 23% of breast cancers evolving in BRCA2 carriers, express a triple negative phenotype." (PMID 32245065, 2020). "In the combined UK MARIBS and NICE studies, in which 45 breast cancers were detected, only two women died of breast cancer (both BRCA1 mutation carriers) after a median follow-up of 12 years." (PMID 33238387, 2020). "As we move into the era of personalized medicine, there is evidence that poly (ADP-ribose) polymerase (PARP) inhibitors exploit homologous recombination (HR) deficiency, especially in breast cancer gene 1 and 2 (BRCA1/2) mutation carriers." (PMID 32455595, 2020). "The first discovered breast cancer predisposition genes, BRCA1 and BRCA2 also turned out to be FANC genes, named FANCS and FANCD1." (PMID 32725171, 2020). "We also investigated subtypes of breast cancer induced by BRCA1/2 germline mutations, as well as their different characteristics." (PMID 32719318, 2020). "Compared with most sporadic breast cancers, those arising in carriers of BRCA1 mutations usually have distinctive pathological characteristics." (PMID 32863939, 2020). "Our study identified a founder pathogenic variant of BRCA1 predisposing to breast cancer and enabled the establishment of an affordable genetic test as a mean of prevention for Senegalese women at risk." (PMID 32025337, 2020). "The young age for development of breast cancer often suggests a genetic predisposition especially germline mutations in BRCA1 and BRCA2 genes." (PMID 32894085, 2020).
breast cancer (continued). "A significant association was found between breast cancer and the GG genotype of the rs1799950 SNP which is located in the BRCA1 gene." (PMID 32711446, 2020). "Germline BRCA1/2 (breast cancer 1/2, early onset) mutations have long been considered an important risk factor for breast cancer." (PMID 33257598, 2020). "Further, individuals with a BRCA1/2 genetic risk of breast cancer can reduce their breast cancer incidence by 50 percent through a salpingo-oophorectomy." (PMID 33255309, 2020). "Around 10–20% of ovarian cancer (OC) and 6% breast cancer (BC) overall are caused by inheritable BRCA1/BRCA2 mutations." (PMID 32708835, 2020). "The Breast Cancer Susceptibility Genes, BRCA1 and BRCA2, have well established roles in the maintenance of genomic stability." (PMID 33015058, 2020). "The current data suggest safety for pregnancy after breast cancer also in BRCA1/2 mutation carriers." (PMID 32719921, 2020). "BRCA1: p.Val1833Met variant was genotyped among 3531 breast cancer patients and 1558 healthy controls using sanger and next generation sequencing, with 27 (0.77%, 27/3531) carriers in cases while no carriers in controls." (PMID 31908633, 2020). "Both breast cancer 1 and breast cancer 2 (BRCA1 and BRCA2) genes are prone to mutation, thought to be due to high densities of repetitive DNA elements." (PMID 32403357, 2020). "There is a well-documented association between women carrying pathogenic germline mutations in breast cancer gene one (BRCA1) or breast cancer gene two (BRCA2) and their risk of developing ovarian cancer." (PMID 32098980, 2020). "The data analysis showed that breast cancer patients presenting BRCA1 mutations were mostly younger (≤ 45 years of age), married, and had positive history of breast feeding and child bearing." (PMID 32063924, 2020). "Germline pathogenic alterations in the breast cancer susceptibility genes 1 (BRCA1) and 2 (BRCA2) are the most prevalent causes of hereditary breast and ovarian cancer." (PMID 32655641, 2020). "Third, gene markers of breast cancer like BRCA1 and BRCA2, are used to stratify patients based on the risk for disease." (PMID 32144248, 2020). "Contradictory results have alsobeen reported for the BRCA1 871L allele, as significantlyassociated with increased risk of breast cancer in a Polish population." (PMID 32453341, 2020). "Basal-like breast cancers commonly carry mutations in genes linked with DNA repair mechanisms like BRCA1, BRCA2, or RAD51." (PMID 33261142, 2020). "Evidence is limited related to food/nutrient intake and breast cancer risk among women with BRCA1/2 pathogenic germline gene variants." (PMID 32165993, 2020). "They suggest that the high risk of contralateral breast cancer in BRCA1/BRCA2 mutation carriers must be taken into account when choosing treatment." (PMID 33019612, 2020). "Following a frameshift mutation of the BRCA1 gene, it is detected that rs80357794 (delC) is strongly correlated with hereditary ovarian and aggressive forms of breast cancer, including TNBC." (PMID 32823908, 2020). "Marker M843 aligned with the breast cancer susceptibility homologue BRCA1 originally identified in Arabidopsis thaliana." (PMID 33370360, 2020). "On the other hand, a recent large study on unselected women with breast cancer in Sweden found a mean age at diagnosis of 50.3 years in women with a pathogenic BRCA1 variant." (PMID 32203205, 2020). "Only 5–10% of breast cancer cases are attributed to inherited mutations (BRCA1, BRCA2, and other breast cancer susceptibility genes)." (PMID 32118013, 2020). "BRCA1/2 gene variants identified in Kenyan breast cancer patients with a family history of cancer evaluated in relation to tumor type and immunohistochemistry used as a proxy for molecular subtype." (PMID 32231682, 2020).
breast cancer (continued). "The observation of familial clustering of breast cancer and subsequent identification of heritable risk attributable to BRCA1 and BRCA2 has had broad impact on risk prediction, precision care, and etiological understanding." (PMID 32251286, 2020). "Loss of BRCA1 nuclear protein was found in a large proportion of sporadic breast cancer tissues, and loss of both cytoplasmic and nuclear BRCA1 protein was observed in approximately 19% of sporadic breast cancer tissues." (PMID 32235451, 2020). "We aimed to clarify the prognostic value of BRCA1/2 mutations on breast cancer-specific outcomes after conventional treatment." (PMID 32322271, 2020). "In patients with advanced breast cancer associated with BRCA1 or BRCA2 mutations, olaparib and talazoparib are now approved for treatment." (PMID 32733560, 2020). "In this study, we have performed simultaneous SNV and CNV analysis in bulk and single cells of BRCA1-deficient breast cancers using WES." (PMID 32978388, 2020). "For example, miR-146a and the G allele of rs2910164 have been correlated with breast cancer risk (odds ratio (OR) = 1.77; 95% confidence interval (CI) = 1.40–2.23) as its predicted binding sites are 3′ untranslated regions of BRCA1 and BRCA2." (PMID 32823908, 2020). "The results showed that a local upregulated estrogen concentration helps the expansion and survival of BRCA1 mutated breast cancer cells." (PMID 33194751, 2020). "PARP inhibitors further synergize with inhibitors of the PI3K pathway, as shown in BRCA-proficient TNBC, BRCA1 mutated breast cancer mouse models, PIK3CA mutated ovarian cancer cells, and PTEN mutated endometrial cancer cells." (PMID 32029455, 2020). "In line with this, it is proven that elongation factor 2 kinase (EF2K) is overexpressed in breast cancer of patients with mutations in BRCA1 (a human tumor suppressor gene), consequently triggering significant tumor growth and poor survival rate." (PMID 33287240, 2020). "Pathologically, familial breast cancers due to BRCA1 mutations differ to those caused by BRCA2 mutations and non-familial breast cancer." (PMID 32025336, 2020). "The pathogenic mutations in BRCA1/2 genes show that breast cancer has hereditary characteristic and increases the risk of getting breast cancer diagnosis." (PMID 33488844, 2020). "Based on the risk of contralateral recurrence and the risk of developing ovarian cancer several years after breast cancer, risk-reducing mastectomy and salpingo-oophorectomy are recommended for BRCA1-c.211dupA carriers." (PMID 33240314, 2020). "The majority of BRCA1-deficient breast cancer cases are classified as triple-negative breast cancer based on the absence of expression of estrogen receptor (ER), progesterone receptor (PR), and HER29, and targeted therapy for this type of cancer is difficult." (PMID 32978388, 2020). "Risk of breast cancer is high in BRCA1/2 mutation carriers, and one or several modifiers with a small effect that is multiplicative can have a significant impact in a high-risk subgroup." (PMID 32140806, 2020). "The breast cancer susceptibility genes (BRCA1 and BRCA2) encode proteins critically involved in the repair of DNA double-strand breaks." (PMID 33109210, 2020). "It has already been shown that this pathway is specifically part of the pathogenesis of breast cancer in BRCA1 mutation carriers." (PMID 32198488, 2020). "SBBC patients with a younger age, family history of breast cancer, or bilateral ER-negative disease are more likely to have BRCA1/2 mutations." (PMID 32117708, 2020). "The aim of this pilot study is to determine for the first time, the prevalence of BRCA1 5382insC founder mutation in a cohort of Egyptian familial breast cancer patients (FBC)." (PMID 32102521, 2020). "To date, the closely related genes to BRCA1/2 mutations in breast cancer remains to be fully elucidated." (PMID 31998560, 2020).
breast cancer (continued). "Breast and ovarian cancers are often linked to a genetic predisposition, most commonly through mutations in the breast cancer susceptibility genes BRCA1 and BRCA2, but also other genes, such as FANCJ/BRIP1, are associated with an increased disease risk." (PMID 32542039, 2020). "Other studies using multigene panels found that over 4% of women at risk of hereditary breast cancer had mutations in genes other than BRCA1/2, including PALB2, CHEK2, and ATM." (PMID 32090079, 2020). "Previous studies have shown that 53BP1 loss is associated with triple-negative and BRCA1 mutated breast cancers." (PMID 32139898, 2020). "Although intuitively it is expected that contralateral prophylactic mastectomy would decrease the risk of contralateral breast cancer, the available data only support this in patients with BRCA1/2 gene mutations." (PMID 31935898, 2020). "Preoperative combination of gemcitabine, carboplatin and iniparib is active in the treatment of early-stage triple-negative and BRCA1/2 mutation-associated breast cancer." (PMID 32391121, 2020). "Data from the Cancer Genome Atlas Program (TCGA) show that ∼ 20% of basal-like breast cancers have a germline and/or somatic BRCA1 or BRCA2 variant." (PMID 33109210, 2020). "Activation of this pathway in BRCA1-deficient breast cancer leads to EMT, cell motility, and tumor progression and metastasis." (PMID 31898540, 2020). "For example, the estimated 10-year risk of developing breast cancer at age 40 years was 17% and 34% for BRCA1 carriers at the 5th and 95th percentiles of the PRS for ER-negative breast cancer, respectively." (PMID 32665703, 2020). "Germline mutations in the breast cancer–susceptibility gene, Breast Cancer 1 gene (BRCA1), significantly increase the risk of developing breast and ovarian cancer, in addition to other forms of cancer." (PMID 32175521, 2020). "There are twenty recurrent mutations in six breast-cancer-predisposing genes in Poland (BRCA1, BRCA2, CHEK2, PALB2, NBN, and RECQL)." (PMID 32824581, 2020). "From a molecular perspective, the majority of these BRCA1-associated breast tumors fall into the “basal-like” subtype of breast cancer, one of the four common intrinsic molecular subtypes." (PMID 33117676, 2020). "Breast cancer risk is elevated up to 72% for BRCA1 and up to 69% for BRCA2 mutation carriers, respectively." (PMID 32719921, 2020). "We confirmed a high risk of breast cancer among young BRCA1 female carriers (almost 30-fold increase for breast cancer at age 40 or below)." (PMID 32824581, 2020). "In order to promote the use of multigene panel testing of breast cancer patients, we need to understand the prevalence of germline mutations particularly in cancer predisposition genes beyond BRCA1/2 to identify the genes commonly mutated in our population." (PMID 32091409, 2020). "About 5% of breast cancer cases are associated with pathogenic variants of the BRCA1 (BRCA1 DNA repair associated, breast cancer type 1 susceptibility) and BRCA2 genes." (PMID 32013256, 2020). "Mutations in BRCA1 confer a high risk for breast cancer, and BRCA1 is involved in many cellular processes as well as in repairing double-stranded DNA breaks (DSBs) mediated by homologous recombination." (PMID 33520689, 2020). "Breast cancers arising in women with a BRCA1 or BRCA2 germline mutation are characterized by genomic instability." (PMID 32711554, 2020). "About 5–10% of breast cancers can be linked to gene mutations inherited from one’s mother or father, such as BRCA1 or BRCA2 mutations." (PMID 32210163, 2020). "After adjusting for age, the odds of a BRCA2 mutation carrier developing MF/MC breast cancer were 3.7‐fold greater than in BRCA1 mutation carriers (CI: 1.77–7.78, p = 0.001)." (PMID 32022473, 2020).
breast cancer (continued). "Joint modeling of both monogenic variant status and polygenic score estimated that the risk for breast cancer among carriers of a BRCA1 or BRCA2 variant ranges from 1.43-fold to 16.68-fold increased risk across percentiles of the polygenic score." (PMID 32820175, 2020). "The OlympiAD trial, which was the global phase 3 trial for metastatic HER2-negative breast cancer with germline BRCA1 or BRCA2 mutations, confirmed that olaparib increased PFS by 2.8 months to 7.0 months (hazard ratio 0.58; P<0.001) and received FDA approval." (PMID 32046300, 2020). "Up to 12% of the cases diagnosed in young patients are hereditary tumours related to germline mutations in the breast cancer susceptibility genes BRCA1 or BRCA2." (PMID 32419845, 2020). "We conducted gene sequencing studies in 23,481 unselected breast cancer cases and 6489 controls and confirmed that BRCA1: p.Ile1845fs variant was associated with increased risk of breast cancer (OR = 2.36, 95%CI = 1.26–4.89, P = 0.004)." (PMID 31908633, 2020). "Around 5–10% of breast cancers are caused by an inherited faulty genes such as the BRCA1 and BRCA2 genes (Cancer Research UK 2014; Cancer Research UK 2018a, b)." (PMID 31965555, 2020). "In cells with loss of function mutations associated with breast cancer susceptibility genes BRCA1 or 2, inhibition of PARP was demonstrated to be synthetically lethal." (PMID 33005627, 2020). "Breast cancers with BRCA1 or BRCA2 mutations are characterized by different gene expression patterns, highlighting the influence of heritable mutations on the phenotype and chemosensitivity of cancer." (PMID 32053991, 2020). "Advanced (T2–T4) breast cancers were more common in BRCA1-mutated cases, compared with those with pathogenic germline mutations in other genes (P = 0.08) or those with no pathogenic variants detected (P = 0.05), especially among younger patients." (PMID 33067557, 2020). "A cumulative risk of contralateral breast cancer of 63% when younger than 40 years of age at first diagnosis of breast cancer, compared to 20% for those who were older than 50 years of age was reported in females carrying a BRCA1 mutation." (PMID 32962297, 2020). "Breast cancer at an early age is more likely to be associated with an increased familial risk, particularly in women with a germline BRCA1 mutation." (PMID 33067490, 2020). "Butsome studies from Chinese populations have reported significant associations betweenthe BRCA1 p.Pro871Leu variant and breast cancer, where the CTgenotype provides increased risk to breast cancer in these populations." (PMID 32453341, 2020). "Our genetic data suggested that BRCA1: p.Ile1845fs was a risk factor for breast cancer with statistically significant OR of 2.36." (PMID 31908633, 2020). "Combined with the discovery and validation stages of breast cancer, 31 cases carried 20 BRCA1/2 variants, with one case (sample ID: 26) harboring two variants." (PMID 32879886, 2020). "Significantly, these mammary tumors are highly proliferative, show ER-negativity and a high degree of genomic instability, similarly to human BRCA1-mutated hereditary breast cancers and sporadic basal-like breast cancers." (PMID 32053991, 2020). "The ability of OPG to bind to RANKL and block its activity raised interest in the role of OPG in BRCA1-mutated breast cancer." (PMID 32318347, 2020). "There are more than 1600 known variants in BRCA1 and its pathogenic variants increase the risks of breast cancer." (PMID 31908633, 2020). "At the same time, we analyzed the difference in patients with breast cancer and ovarian cancer mutated in BRCA1 or BRCA2 or who were wild-type." (PMID 32195358, 2020). "Mice harboring the BRCA1 mutation in luminal epithelial progenitors develop tumors that resemble human BRCA1-associated breast cancer, while BRCA1-mutated basal cells develop distinct tumors." (PMID 33299637, 2020).